IL4 (interleukin 4)
Diseases named in the same sentence as IL4 in open-access papers (continued):
Sharing a sentence is not in itself a finding about the gene and the disease.
tumor (continued). "In the reported breast cancer study using an orthotopic tumor model, the authors demonstrated that IL-6 and IL-4 secretion by these stromal cells facilitates tumor progression and immune modulation." (PMID 40453074, 2025). "Hypoxia can reprogram macrophage metabolism, pushing them toward an M2-like, tumor-promoting phenotype due to IL-4 and IL-10 secretions or impairing their survival." (PMID 40698077, 2025). "Interleukin-4 (IL-4) is crucial in inhibiting anti-tumor immune responses and facilitating tumor cell proliferation, while the Hh pathway enhances IL-4 expression by stimulating T-helper 2 (Th2) cells transcription." (PMID 40557151, 2025). "The type 2 cytokines IL-4 and IL-13 released by macrophages, MDSCs or even tumor cells, maintain the TAMs in an immune suppressed state." (PMID 40236693, 2025). "Th2 cells produce interleukin (IL)-4 and IL-13, which inhibit cytotoxic T-cell function and diminish anti-tumor immune responses." (PMID 40740231, 2025). "Eosinophil depletion further supports an immunosuppressive phenotype, as eosinophils contribute to anti-tumor immunity via cytokine release (e.g., IL-4, IL-5) and direct cytotoxicity." (PMID 41301691, 2025). "In the tumor microenvironment, IL-4 and IL-13 also polarize macrophages toward an M2 phenotype, which supports tumor growth and suppresses anti-tumor immunity." (PMID 40981274, 2025). "While generally immunosuppressive, under certain circumstances, IL-4 can paradoxically enhance anti-tumor immunity." (PMID 40864740, 2025). "The findings of this study highlight a marked increase in IL-4 levels in LNCaP-Doc/R cells, underscoring its potential role in driving tumor progression." (PMID 40507238, 2025). "The analysis revealed a significantly higher number of tumor-infiltrating CD45.1+cells in the FL/GM-DC group compared to the GM/IL4-DC group at all three time points." (PMID 40977690, 2025). "M1-macrophages are induced by IFN-γ or LPS and have tumor suppressive functions, whereas M2-macrophages are stimulated by IL-4 and support tumor growth, angiogenesis and metastasis." (PMID 40356913, 2025). "Among Th subsets, Th1 cells mediate cytotoxicity via interferon-gamma (IFN-γ), while Th2 and Th17 cells, through IL-4, IL-13, and IL-17, support tumor progression." (PMID 41383623, 2025). "Taken together, the results of our study suggest that increased levels of IL-33 and IL-4 are responsible for the development of a less favorable type 2 anti-tumor immune response, which contributes to worse therapeutic response." (PMID 40943444, 2025). "The M2-type TAMs are induced by IL-4 and IL-10, which display both anti-inflammatory and pro-tumor functions." (PMID 40709184, 2025). "In B16 melanoma, IL-4 production indirectly promotes tumor growth by inhibiting the cytotoxicity of additional antitumor γδ T-cell populations." (PMID 40558272, 2025). "We demonstrate that the use of IL-4+ tumor-specific T cells in a murine ACT model is an effective means of targeting this tumor subtype." (PMID 40367186, 2025). "We found several key anti-tumor Th1 cytokines such as interleukin (IL)-2, IL-4, and interferon-γ, were stimulated by the combination therapy either systemically or in tumors or both, as well as anti-tumor biomarkers such as Granzyme B and perforin." (PMID 40104170, 2025). "It is still unclear how IL-4 pathway modulation—when combined with BV—affects anti-tumor immunity and long-term surveillance." (PMID 40864740, 2025). "On the other hand, IL-4 has also been reported to inhibit cell apoptosis, potentially promoting tumour growth." (PMID 39325360, 2025). "Tumor size, survival time, dendritic cells (DCs) count, serum cytokine levels (IL-4, IFN-γ), and the Th1/Th2 ratio (IFN-γ/IL-4) were compared among the four groups." (PMID 40666179, 2025). "Simultaneously, mice were engrafted with either 1 or 10% of cells expressing IL-4 and 99 and 90% of B16.IFNα4.gB.luc cells, respectively, had a significant increase in tumor free survival compared to controls." (PMID 40367186, 2025).
tumor (continued). "Knockout of the IL-4 receptor (IL4rα) reduced physical interactions between tumor cells and IL4rα-deficient macrophages, correspondingly decreasing metastatic foci, indicating that IL-4 regulates macrophage-tumor cell interactions." (PMID 40995371, 2025). "IL-4 exerts broad effects on tumor biology by modulating the tumor microenvironment (TME) and promoting immune evasion." (PMID 40864740, 2025). "Research has shown that interleukin-4 activates macrophages, which in turn upregulate PD-L1 expression in tumor cells." (PMID 40924249, 2025). "In contrast, the M2 phenotype, characterized by the expression of cytokines such as interleukin-4 (IL-4), interleukin-13 (IL-13), and IL-10, exhibits tumor-promoting and angiogenic functions." (PMID 40918147, 2025). "With these carboxylic acid-modified derivatives in hand, we investigated their impact at 10 μM on ARG1 and NOS2 mRNA expression in RAW 264.7 cells pre-stimulated with IL-4/IL-13 to evaluate the effects on the pro-tumor phenotype of macrophages." (PMID 40430260, 2025). "By analyzing gene expression in GBM PNZ and tumor cells under ischemic conditions, our studies found that IL-4 and IL-13 signaling are the top-activated pathways." (PMID 39805854, 2025). "On TAMs, TIM-3 regulates tumour biological behaviour by enriching IL-4, which has anti-inflammatory and pro-tumour effects." (PMID 40994140, 2025). "To validate the ability of ex vivo-differentiated DCs to present tumor antigens and activate T cells, we pulsed FL/GM-DCs and GM/IL4-DCs with B16-OVA tumor lysates, then co-cultured those pulsed DCs with CD8+T cells isolated from OT-I transgenic mice." (PMID 40977690, 2025). "In contrast, Th2 cells produce IL-4, a cytokine that promotes tumor cell growth and enhances metastatic potential." (PMID 40918463, 2025). "The IL-4/STAT6 axis plays a pivotal role in tumor development and the establishment of an immunosuppressive milieu." (PMID 40864740, 2025). "Interleukin-4 (IL-4) exerts a dual effect in human PC, acting both directly on the tumor cells themselves and indirectly within the TME." (PMID 40948749, 2025). "The authors identified IL4 KO tumor cells among the genetic clones with a significant reduction in relative abundance only in context of immune checkpoint blockade, suggesting that IL-4 promotes resistance to anti-PD-1 treatment." (PMID 39837825, 2025). "This shift was associated with decreased pro-inflammatory cytokines (IL-1β, TNF-α) and increased anti-inflammatory cytokines (IL-10, IL-4), along with suppression of tumor-promoting pathways and improved intestinal barrier integrity." (PMID 40417220, 2025). "While Tregs inhibit anti-tumor immunity through IL-10 and TGF-β, a dominant Th2 response (IL-4, IL-10) is associated with tumor growth." (PMID 41018485, 2025). "Another possible pro-tumor pathway involves IL-4 and IL-10 secretion, which is connected with Vδ1 T cells exhibiting a regulatory phenotype and inhibiting Vδ2 T cell function." (PMID 40148988, 2025). "In a subsequent phase, M1 macrophages are influenced by Th2 cytokines such as interleukin 4 (IL-4) and IL-13 to polarize at tumor sites, leading to their transformation into M2-type macrophages." (PMID 40264760, 2025). "IL-4 contributes to tumor growth via several mechanisms, including reducing interferon-gamma (IFN-γ) production and upregulating anti-apoptotic genes in tumor cells, supporting their survival and growth." (PMID 40864740, 2025). "GSEA using Reactome terms identified increased interleukin activity of tumor-infiltrating DCs with IL4, IL13, and IL10 predicted to elicit the greatest impact on infiltrating DCs." (PMID 39932553, 2025). "Th2 cells complement this by activating the IL-4/Gata3/STAT6 axis, inducing genes linked to proliferation and metastasis, and promoting integrin-mediated tumor invasion." (PMID 40510347, 2025).
tumor (continued). "Th2-polarized CD4+ T cells produce cytokines (e.g. IL-4, IL-13) that can dampen Th1 responses and impair the function of cytotoxic T lymphocytes, thereby weakening the immune system’s ability to attack tumor cells." (PMID 41403933, 2025). "Cytokine proteome profiling revealed that OXP-treated ASCs significantly influenced the tumor microenvironment by promoting immune evasion (via IL-4, GM-CSF, IP-10, and GROα) and driving extracellular matrix remodeling (through EMMPRIN and DPPIV)." (PMID 39796244, 2025). "Th2 cells produce interleukin-4 and exert strong anti-cancer effects, partly by promoting tumor stromal remodeling and tissue repair." (PMID 41614807, 2025). "Conversely, in certain tumor contexts, IL-4 and IL-13 contribute to the activation and survival of cytotoxic T lymphocytes and natural killer (NK) cells, supporting immune surveillance against malignant cells." (PMID 40981274, 2025). "Research has also highlighted the influence of NSCLC subtypes on IL-4 mRNA levels, emphasizing the diverse effects of cytokines across the tumor microenvironment, both promoting and inhibiting tumor immunity and growth." (PMID 41179937, 2025). "In tumor tissues, expression levels of IL-4, IFN-γ, and perforin, an indicator of anti-tumor cytotoxicity, were significantly increased by several treatment groups, while the triple treatment significantly upregulated the expression of IFN-γ." (PMID 40104170, 2025). "For instance, the administration of Fc–IL‐4 alongside OT1 T‐cell therapy achieved complete tumour clearance (100%) in the YUMM1.7‐OVA melanoma model." (PMID 39739593, 2025). "A recent study by Stewart and colleagues found IL-4 contributes to CAR T cell dysfunction and exhaustion; IL-4 neutralization enhanced anti-tumor effectiveness in vitro and in vivo while reducing exhaustion markers." (PMID 41346587, 2025). "In conjunction with elevated IL2, which can enhance the cytotoxic activity of NK and T cells, and decreased IL4, which associates with an immunosuppressive TIME, these alterations boost anti-tumor immunity and reverse T cell exhaustion." (PMID 40666944, 2025). "Evaluating the equilibrium between IFN-γ and anti-inflammatory cytokines (IL-4 + IL-10 + IL-13) revealed tumor progression is accompanied by an increased inflammatory balance in 4T1 tumors (P=0.0004), in contrast to MC4-L2 tumors." (PMID 39877637, 2025). "Upregulation of Bcl-2 and Bcl-xL via IL-4/STAT6 signaling is therefore a key mechanism by which tumor cells evade apoptosis and sustain their growth under therapeutic pressure." (PMID 40864740, 2025). "We simultaneously analyzed the expression of TAP2 protein, IL-4 mRNA, CD11b mRNA and CK protein in tumor specimens from the NSCLC Cohorts #1 and #2." (PMID 40091029, 2025). "Tumor progression was monitored, evaluated immune responses by measuring cytokine levels (including IL-4, IFN-γ, and IL-12), and investigated the presence of CD8 + T cells within the tumors." (PMID 40403026, 2025). "This highlights the potential benefit of combining IL-4 pathway inhibitors with ICB or other immunotherapies such as Brentuximab Vedotin to overcome tumor immune evasion." (PMID 40864740, 2025). "In vitro, BBR suppressed IL-4 or tumor cell supernatant-induced M2 polarization, as evidenced by decreased expression of M2 polarization marker genes (Arg1, Retnla, etc.)and reduced JAK1/STAT6 phosphorylation levels." (PMID 41585886, 2025). "Conversely, anti-inflammatory cytokines such as IL-4 and IL-10 can suppress immune surveillance while paradoxically supporting tumor progression through immunosuppressive mechanisms." (PMID 41614846, 2025). "In a tumor-cell-only model, the roles of IL4 and IL8 would likely appear less central compared to their significance in the complex in vivo GBM microenvironment." (PMID 41031155, 2025).
tumor (continued). "In ascitic CD4+ T cells of tumor‐bearing mice, Tnfrsf14 knockdown resulted in a reciprocal increase in IFNγ‐producing Th1 cells and a decrease in IL4‐producing Th2 cells, whereas the levels of IL17‐producing Th17 cells remained similar." (PMID 40105652, 2025). "To identify the cellular source of IL-4, we spatially mapped the IL-4 mRNA production in the tumor microenvironment of human NSCLCs using QIF." (PMID 40091029, 2025). "IL-4 has been shown to upregulate anti-apoptotic proteins like Bcl-xL and cFLIP, enabling tumor cells to evade chemotherapy-induced cell death." (PMID 41366282, 2025). "Consequently, IL-4/IL-13 blockade may theoretically reduce tumor risk." (PMID 40843371, 2025). "Multiple cytokines, including IL-2, IL-12, IL-10, and IL-4, showed significant reduction in tumor tissues derived from Gsdmd–/– mice compared with WT mice." (PMID 40759573, 2025). "This is consistent with established evidence attributing IL-4-induced tumor growth to diverse cellular mechanisms in hematopoietic, endothelial, and various tumor cell lines." (PMID 40507238, 2025). "The Th2-dominant tumor microenvironment (TME) in MF features elevated IL-4 and IL-13, which promote malignant T cell survival and suppress cytotoxic responses." (PMID 40864740, 2025). "ILC2s promote tumor progression by secreting IL-4 and IL-13, which activate the IL-4Rα–STAT6 signaling pathway." (PMID 40497988, 2025). "In human and mouse NSCLC, IL-4 derived from bone marrow basophils and eosinophils promoted the development of immunosuppressive tumor-promoting myeloid cells." (PMID 40873585, 2025). "Studies have shown that in the tumor microenvironment, M2 macrophage polarization is regulated by various cytokines such as IL-4, IL-13, and the STAT6/C/EBPβ signaling pathways." (PMID 40433361, 2025). "This was demonstrated by increased DNA binding activity, phosphorylation of STAT6, and higher expression levels of IL-4, IL-4Rα, and p21 in their tumor tissues." (PMID 40636453, 2025). "This study identified IL-4 as a key tumor-derived factor that drives macrophage polarization, particularly promoting the MARCO-expressing macrophage subset in the ovarian tumor microenvironment." (PMID 40330466, 2025). "The IL-4 transgenic mice displayed smaller tumor volumes and weights and showed enhanced activation of the STAT6 pathway." (PMID 40636453, 2025). "Future research should prioritize preclinical models to test the safety and efficacy of combining IL-4 pathway inhibition with BV, with a particular focus on tumor microenvironment remodeling, CD30 expression kinetics, and cytotoxic immune function." (PMID 40864740, 2025). "In this study, we further showed that calcipotriol-induced TSLP activates Th2 cells to release IL-4, which in turn promotes IL-24 production by TAMs, resulting in tumor cell apoptosis." (PMID 39782693, 2025). "Under physiological conditions, IL-4 functions as an anti-inflammatory cytokine that maintains immune homeostasis, yet within the tumor microenvironment, it can activate the Akt signaling pathway, promoting cancer cell survival." (PMID 41155372, 2025). "MφU-SNFIB-MAA-CIT- stimulated HCAECs exhibited upregulation of tumor microenvironment pathways, IL-4 and IL-13 signaling, inflammation signaling, and fibrosis signaling, with concurrent downregulation of IL-10 signaling pathways." (PMID 41296447, 2025). "The shift toward a Th2 response leads to increased levels of IL-4 and IL-10, weakening the cellular immune response needed to combat intracellular pathogens and tumor cells." (PMID 39857306, 2025). "In our coculture system, BV2 microglia and IL‐4‐treated BMDMs occupied the cluster periphery and pushed tumor cells together, as shown in a time‐lapse video." (PMID 40747560, 2025). "In vitro co-culture of splenocytes with tumor lysates did increase IL-4, although IFN-γ remained unchanged." (PMID 41012179, 2025).
tumor (continued). "This phenomenon is mediated by various tumor-derived factors, including cytokines (e.g., IL-4, IL-10, TGF-β) and chemokines, which collectively promote M2 polarization of macrophages." (PMID 41019043, 2025). "Dupilumab, a monoclonal antibody originally designed to treat a wide range of inflammatory conditions, reduces the IL-4-induced pro-tumor phenotype of TAMs by binding to the IL-4 receptor alpha subunit (IL-4Rα) to block IL-4 signaling." (PMID 40699676, 2025). "In our direct co-cultures, we observed an early increase in IFN-γ secretion and enhanced tumor cell killing activity, followed by a decrease in IL-1β, IL-4 and IL-6 levels alongside an increase in soluble CXCL1." (PMID 40108668, 2025). "Tumor cell derived IL-4 fostered an immunosuppressive TME, characterized by tumor-associated M2 macrophages and limited T cell infiltration." (PMID 39837825, 2025). "For instance, Vera and colleagues improved CAR T-cell function by introducing an IL-4/IL-7 invert cytokine receptor (ICR) to counteract the immunosuppressive tumour microenvironment in pancreatic cancer." (PMID 40335685, 2025). "In these tumors, an increased Th2/Th1 ratio within cold tumors was observed, and co-staining IL4 and CD117 showed that IL4 + MCs were significantly (P = 0.01) higher in tumor-draining LNs in cold tumors compared to hot tumors." (PMID 40175843, 2025). "Th2 cells primarily secrete IL-4, IL-6, and IL-10; IL-4 regulates MDSCs by synthesizing arginase 1 (Arg1) and decomposing l-arginine to induce T-cell apoptosis and tumor immunosuppressive effects." (PMID 41278263, 2025). "Conversely, M2-like TAMs are driven by IL-4, IL-13, and IL-10, and promote tumor progression by releasing immunosuppressive factors (PGE2, TGF-β, IL-10), and pro-angiogenic mediators (FGF, PDGF, VEGF)." (PMID 41383623, 2025). "This provides a strong basis for restoring tumor sensitivity to immunotherapy by exogenous introduction of Fc-IL-4." (PMID 41226585, 2025). "By directly suppressing Th1 cytokines and promoting MF tumor cell survival and proliferation (often in conjunction with IL-13), IL-4 enables immune evasion, chronic inflammation, and fibrosis in the skin." (PMID 40864740, 2025). "The translational relevance of these findings was provided showing that IL4 expressing basophils increased in tumor-draining lymph nodes (TDLN) of PDAC patients." (PMID 40873585, 2025). "PC cells serve as both a source and target of IL-4, creating an autocrine loop that directly promotes tumor cell proliferation." (PMID 40948749, 2025). "IL-4’s anti-tumour effects are primarily mediated through eosinophils and macrophages, whereas IL-13’s anti-tumour activity is reported to be mediated by neutrophils and macrophages." (PMID 39325360, 2025). "For example, the intense initial inflammatory activity of M1 macrophages in tumors is regulated by Th2 cells and cytokines such as IL-4 and IL-10 to achieve an effective yet controlled anti-tumor response." (PMID 41463479, 2025). "By contrast, Th2 cells support humoral responses via IL-4, IL-10, and IL-13, suppressing Th1-mediated responses and fostering an immunosuppressive tumor microenvironment." (PMID 41176307, 2025). "Th2 cells can activate M2 macrophages and secrete inflammatory factors such as IL-4 and IL-5, which promote tumor progression." (PMID 41471272, 2025). "In B cell malignancies, the lymph nodes are a critical site of pathology and the T cell-derived signals CD40L and IL-4 within the lymph node microenvironment can mediate tumour proliferation, survival and resistance to pro-apoptotic therapy." (PMID 40977848, 2025). "We demonstrate that the adoptive transfer of IL-4+ tumor-specific T cells can successfully target this phenotype." (PMID 40367186, 2025). "During macrophage recruitment to tumours, tumour microenvironment (TME) factors like interleukin-4, can induce CatS activity." (PMID 40265075, 2025).